JARID2 (jumonji and AT-rich interaction domain containing 2)
Diseases named in the same sentence as JARID2 in open-access papers (continued):
Sharing a sentence is not in itself a finding about the gene and the disease.
neurodevelopmental disorder (3 papers, 2022 to 2024). A behavioral and cognitive disorder with onset during the developmental period that involves impaired or aberrant development of intellectual, motor, or social functions. "All the samples with (likely) pathogenic JARID2 variants received MVP scores near 1, while all the control samples and case samples from other neurodevelopmental disorders received low MVP scores." (PMID 35887345, 2022). "In addition, we performed analysis of functional correlation of the JARID2 genome-wide methylation profile with the DNA methylation profiles of 56 additional neurodevelopmental disorders." (PMID 37762546, 2023). "However, JARID2 may be directly associated with HHV-6 infection and indirectly with neurodevelopmental disorders, potentially increasing the risk of developing MDD." (PMID 39420919, 2024).
genetic disorders (1 paper, 2022). "The classifier was constructed by training the 8 case samples with (likely) pathogenic JARID2 variants against the 56 matched control samples (used for probe selection), 75% of other control samples, and 75% of case samples from 57 other rare genetic disorders." (PMID 35887345, 2022). "In addition, the JARID2 signature can be added to the growing list of syndromes that can be confirmed by EpiSign analysis, thus further confirming the value of EpiSign as a diagnostic tool in patients with suspected genetic disorders." (PMID 35887345, 2022).
psychiatric disorder (1 paper, 2023). A disorder characterized by behavioral and/or psychological abnormalities, often accompanied by physical symptoms. "The human JARID2 gene is located in 6p22.3 and is associated with numerous psychiatric disorders and neurodevelopment." (PMID 38203196, 2023). "The Jumonji and structural domain-rich AT interaction domain 2 (JARID2) gene plays an important role in neurodevelopment in mice and various psychiatric disorders in humans." (PMID 38203196, 2023). "Therefore, the JARID2 gene plays an important role in the development of the nervous system and the occurrence of human psychiatric disorders." (PMID 38203196, 2023).
JARID2 also shares sentences with these, for which no sentence is quoted: Intellectual disability (4 papers); acute myeloid leukemia (1); Aicardi syndrome (1); allergic rhinitis (1); bipolar disorder (1); cleft lip (1); colitis (1); congenital heart defects (1); depression (1); dilated cardiomyopathy (1); Ewing sarcoma (1); heart diseases (1); hepatocellular adenoma (1); lactic acidosis (1); lung squamous cell carcinoma (1); microcephaly (1); myeloid malignancies (1); myopathy (1); oral cancers (1); oral squamous cell carcinoma (1); Pulmonic stenosis (1); sideroblastic anemia 2 (1); speech delay (1); thyroid cancer (1); tuberous sclerosis (1); ventricular septal defect (1); Weaver syndrome (1).